FHL2 (four and a half LIM domains 2)
Description:
May function as a molecular transmitter linking various signaling pathways to transcriptional regulation. Negatively regulates the transcriptional repressor E4F1 and may function in cell growth. Inhibits the transcriptional activity of FOXO1 and its apoptotic function by enhancing the interaction of FOXO1 with SIRT1 and FOXO1 deacetylation. Negatively regulates the calcineurin/NFAT signaling pathway in cardiomyocytes.
Synonyms: FHL-2; SLIM-3; DRAL; SLIM3; AAG11
Tractability: PROTAC: UniProt records ubiquitination sites on it; ubiquitination databases record sites on it.
Gene: Protein-coding gene on chromosome 2 (105,357,712 to 105,438,585, reverse strand). Ensembl gene ENSG00000115641.
Subcellular location: Cytoplasm; Nucleus; Cytoplasm, myofibril, sarcomere, Z line
Subcellular location (Human Protein Atlas): Actin filaments; Focal adhesion sites
Pathways (Reactome):
Metabolism: PPARA activates gene expression
Gene Ontology:
Molecular function: identical protein binding; protein binding; transcription factor binding; bHLH transcription factor binding; transcription corepressor activity
Biological process: negative regulation of apoptotic process; negative regulation of calcineurin-NFAT signaling cascade; negative regulation of transcription by RNA polymerase II; response to hormone; atrial cardiac muscle cell development; heart trabecula formation; osteoblast differentiation; ventricular cardiac muscle cell development
Cellular component: actin cytoskeleton; cytoplasm; focal adhesion; nucleus; nucleoplasm; Z disc
Genetic constraint (gnomAD): Loss-of-function variants: 20 observed, 34.45 expected, observed/expected ratio (o/e) 0.58, 90% interval 0.41 to 0.84. The upper end of that interval is the gene's LOEUF score, 0.84, which puts it in group 3 of 6, group 1 being the genes least tolerant of losing a copy. Missense variants: 306 observed, 368.75 expected, observed/expected ratio (o/e) 0.83, 90% interval 0.75 to 0.91. Synonymous variants: 119 observed, 133 expected, observed/expected ratio (o/e) 0.89, 90% interval 0.77 to 1.04.
Homologues: Orthologues: chimpanzee FHL2 (99% identical), dog FHL2 (93% identical), mouse Fhl2 (92% identical), rat Fhl2 (91% identical), guinea pig FHL2 (87% identical), tropical clawed frog fhl2 (85% identical), zebrafish fhl2a (82% identical), zebrafish fhl2b (81% identical), macaque FHL2 (69% identical), rabbit FHL2 (66% identical), Caenorhabditis elegans lim-9 (56% identical). Paralogues in human: FHL5 (60% identical), FHL3 (53% identical).
Diseases named in the same sentence as FHL2 in open-access papers:
FHL2 is named in the same sentence as 144 diseases in open-access papers, as found by Europe PMC text mining. Sharing a sentence is not in itself a finding about the gene and the disease. The quoted sentences say what the papers report.
cardiac hypertrophy (18 papers, 2014 to 2025). "Although FHL2-deficient mice maintain normal cardiac function they display cardiac hypertrophy in response to β-adrenergic stimulation." (PMID 24736599, 2014). "Furthermore, FHL2 was originally identified in the heart, and the association of FHL2 mutations with human cardiac hypertrophy reinforce both its importance in the heart and its relevance to human cardiac disease." (PMID 28714941, 2017). "Both FHL1 and FHL2 have not only been linked to cardiac hypertrophy signaling but also bind titin." (PMID 27889803, 2016). "Based on evidence that FHL2 (four and a half LIM domains protein 2) negatively regulates cardiac hypertrophy we tested whether FHL2 altered expression or variants could be associated with hypertrophic cardiomyopathy (HCM)." (PMID 25358972, 2014). "Among these gene pairs, IDH2 has been shown to play a role in preventing oxidative stress in cardiac hypertrophy in mice and FHL2 has been shown to repress pathological cardiac remodeling." (PMID 38780967, 2024). "FHL2 is commonly believed to be specifically expressed in adult human CMs-V and plays a significant role in promoting myocardial hypertrophy." (PMID 38542214, 2024). "FHL2, located at the sarcomere, interacted with extracellular signal regulated kinase (ERK) and regulated cardiac growth, suggesting FHL2 a protective role in adrenergic-mediated cardiac hypertrophy." (PMID 32682418, 2020). "FHL2 has been described to prevent extracellular signal-regulated kinase (ERK)-induced cardiac hypertrophy through binding and inhibiting ERK in cardiomyocytes." (PMID 24736599, 2014). "FHL2 deficient mice exhibited normal response to short-term TAC, but developed exaggerated cardiac hypertrophy under chronic isoprenaline stimulation, suggesting that the implication of FHL2 in heart failure depends on the trigger inducing heart failure." (PMID 25358972, 2014). "This supports previous findings of reduced FHL2 protein levels in AngII-induced cardiac hypertrophy in mice and in failing human hearts." (PMID 25358972, 2014). "Whereas it was reported that FHL2 is up-regulated upon adrenergic stimulation in vivo in rodents, FHL2 protein abundance was markedly reduced in angiotensin II (AngII)-induced cardiac hypertrophy in mice and in human heart failure." (PMID 25358972, 2014). "Nevertheless, while FHL2 knockouts displayed greater cardiac hypertrophy following catecholamine stimulation, global loss of the protein is well tolerated, and the hypertrophic response following transverse-aortic constriction (TAC) was indistinguishable from that of controls." (PMID 34745373, 2021). "Indeed, overexpression of FHL2 in isolated cardiomyocytes was shown to reduce cardiac hypertrophy due to Mek1, Gata4 and phenylephrine stimulation." (PMID 34745373, 2021). "Additionally, changes indicative of cardiac hypertrophy and heart failure, e.g. Fhl1 upregualtion and Fhl2 downregulation, Carp induction) and upregulation of β-myosin heavy chain were observed at the protein level in the myocardium of KI/KI mice." (PMID 30048712, 2018). "This supports the previously suggested role of FHL2 as a negative regulator of cardiac hypertrophy." (PMID 25358972, 2014). "Thus the roles that FHL1 and FHL2 play in regulating cardiac hypertrophy in the in vivo setting may be isoform-specific and dependent on the nature of the stress stimulus that triggers the hypertrophic response." (PMID 24219103, 2014). "Gene expression of Four and a half LIM domains protein 2 (FHL2), a cardioprotective regulator of cardiac hypertrophy, decreased in in the RV at 3 and 6 months and in the LV at all time points, compared to control." (PMID 33716758, 2021). "Interestingly, at least in some settings, FHL1 and FHL2 appear to have differential effects on cardiac myocyte ERK activity, raising the possibility that the ERK pathway may be critical in mediating the regulation of cardiac hypertrophy by FHL proteins." (PMID 24219103, 2014).
cardiac hypertrophy (continued). "FHL2 belongs to the LIM-domain only proteins, and the absence of FHL2 exaggerated isoproterenol-induced cardiac hypertrophy." (PMID 35910357, 2022). "A plausible interpretation of such data is that PKD1 regulates cardiac hypertrophy through a mechanism that is independent of its kinase activity, in which case FHL1- and FHL2-mediated regulation of neurohormonal PKD activation would be more likely to regulate other PKD-mediated functions." (PMID 24219103, 2014).
breast cancer (15 papers, 2008 to 2023). A primary or metastatic malignant neoplasm involving the breast. "A closer look at the eight Ox-E/ER genes linked to these growth factors revealed that most (EGR1, PHLDA1, IGFBP5, TAGLN, DAB2, and FHL2) have been associated with breast cancer." (PMID 18631401, 2008). "Previous studies have shown that FHL1 binds the oestrogen receptor transcription factor to regulate breast cancer cell growth and that the binding of FHL2 to the transcription factor E4F1 inhibits its transcriptional regulation and promotes cell proliferation." (PMID 36418297, 2022). "In MDA-MB 231 breast cancer cell lines, overexpression FHL2 promoted cancer development by mediating transcriptional activation of MAPK target genes." (PMID 33092075, 2020). "The G2/M transition was found to be accelerated when FHL2 expression is suppressed in breast cancer MDA‐MB 231 cells, and the induction of the FHL2 target gene, the cell cycle inhibitor p21, was responsible for this event when cells were treated with the DNA damaging agent doxorubicin." (PMID 33932144, 2021). "The function of FHL2 in cancers is particularly intriguing because FHL2 can function as an oncoprotein or as a tumor suppressor in different type of cancers, including prostate cancer, liver cancer, gastrointestinal cancers, breast cancer and osteosarcoma." (PMID 25121502, 2014). "Notably, FHL2 was found to be increased in breast cancer, glioma, lung cancer, colon carcinoma and gastrointestinal cancer compared to normal tissues." (PMID 23383046, 2013). "Indeed, breast cancer patients with tumors expressing low amounts of FHL2 have a better survival compared to those with high intra-tumoral FHL2 expression and activation of nuclear FHL2 signalling is linked to aggressiveness and recurrence of prostate cancer." (PMID 20442768, 2010). "FHL2 can promote cell proliferation in some cell types, such as glioblastoma cells, ovarian granulosa cells, and tongue squamous cells, but antagonizes cell proliferation in other cell types, such as breast cancer cells (MCF‐7), colon cancer cells (HT‐29), and smooth muscle cells (SMCs)." (PMID 33932144, 2021). "The expression patterns of FHL2 are different in different cancer types and FHL2 has been shown to be down-regulated in some cancer forms such as prostate cancer and acute myeloid leukemia whilst up-regulated in others such as breast cancer, ovarian cancer, cervical cancer and colon cancer." (PMID 34295384, 2021). "FHL2- is a member of the four-and-a-half-LIM-only protein family, found over-expressed in BC cell lines upon DAC; it can inhibit the proliferation and invasive growth of human breast cancer cells by repressing the functional activity of an inhibitor of DNA binding 3 (ID3)." (PMID 25077705, 2014). "In fact, the DNB method reveals the existence of the pre-transition state, which, however, may not be detected by molecules such as EGR4, FOSL-1, FHL2, and DIPA, although these four transcription factors are proved to be effective for indicating the differentiation of breast cancer cells." (PMID 26284108, 2015).
colon carcinoma (15 papers, 2008 to 2023). "In addition, FHL2 has been demonstrated to promote epithelial-mesenchymal transition (EMT) in colon cancer cells which is known to be associated with cancer progression and metastasis." (PMID 34295384, 2021). "In addition, down-regulation of E-cad by FHL2 is associated with EMT in colon cancer." (PMID 34295384, 2021). "Algaber and co-workers found that inhibition of FHL2 expression using a miR-340-5p mimic increased E-cadherin expression and reduced colon cancer cell migration and invasion." (PMID 38203664, 2023). "In colon cancer and osteosarcoma, FHL2 can make nuclear β-catenin stable, prompting β-catenin transactivation activity." (PMID 36227138, 2022). "FHL2 has been reported to play important roles in different cells’ differentiation, including neuronal cells, gastric and colon cancer cells, and limb mesodermal progenitors, and BRCA2 regulates the differentiation of both normal tissues and different cancers." (PMID 36428735, 2022). "In order to achieve a clear knock-down phenotype for endogenous FHL2 and to be able to study the contribution of p57, we selected the colon carcinoma cell line HRT-18, where FHL2 and p57 are expressed." (PMID 33928088, 2021). "Taken together, we conclude that expression of FHL2 in stressed cancer cells play an important role in colon cancer cell migration and invasion." (PMID 34295384, 2021). "Herein, we show for the first time that FHL2 acts as an important regulator in colon cancer cell migration and invasion under specific conditions." (PMID 34295384, 2021). "This study shows that inhibition of FHL2 expression by using miR-340-5p mimic reduces colon cancer cells migration and invasion." (PMID 34295384, 2021). "In the present study, we found that transfection of colon cancer cells with miR-340-5p mimic reduced colon cancer cell migration and invasion via FHL2." (PMID 34295384, 2021). "To study stress-induced changes in HT-29 and AZ-97 colon cancer cell lines, we cultured both cell lines in low-serum (stress) and serum-rich condition and evaluated FHL2 mRNA expression." (PMID 34295384, 2021). "We used two microarray based large datasets to compare FHL2 expression between colon cancer and normal colon tissue while the other studies, reporting higher expression of FHL2 in colon cancer, used western blot and immunohistochemistry." (PMID 34295384, 2021). "FHL2 expression was therefore assessed in colon cancer microarray datasets using Qlucore omics explorer as well as in HT-29 and AZ-97 colon cancer cell lines via reverse transcription-quantitative PCR (RT-qPCR)." (PMID 34295384, 2021). "Knowing that FHL2 expression is different in different tissues, we first compared FHL2 expression between normal colon mucosa and colon cancer in different datasets." (PMID 34295384, 2021). "It should be noted that FHL2 expression is documented to promote colon cancer cells invasiveness by transforming epithelial cells to mesenchymal cells." (PMID 34295384, 2021). "Considering the fact that FHL2 regulates cancer cell migration and proliferation, these findings indicate that miR-340-5p regulates colon cancer progression with an inverse relationship to FHL2 expression and cell proliferation." (PMID 34295384, 2021). "Confocal microscopy and RT-qPCR were subsequently performed to assess FHL2, E-cadherin (E-cad) protein and mRNA expression in colon cancer cells." (PMID 34295384, 2021). "We observed that this short serum exposure increased FHL2 expression in colon cancer cells and that transfection of cells with miR-340-5p mimic significantly reduced serum-induced FHL2 expression both in mRNA and protein levels." (PMID 34295384, 2021). "Herein, we first analyzed two colon cancer related microarray datasets and found that FHL2 expression was down-regulated in primary colon cancer compared to matched normal colonic mucosa." (PMID 34295384, 2021).
colon carcinoma (continued). "We utilized two different cells lines (HT-29 and AZ-97) representing low and relatively high FHL2 expressing colon cancer cells for our subsequent stress related study." (PMID 34295384, 2021). "Surprisingly, we found that serum condition provoked FHL2 expression in both colon cancer cell lines." (PMID 34295384, 2021). "Microarray dataset analysis revealed that FHL2 expression was lower in primary colon cancer cells compared with normal colonic mucosa." (PMID 34295384, 2021). "Expression of miR-340-5p and FHL2 were assessed in HT-29 and AZ-97 colon cancer cell lines in low-serum (to mimic stress condition of tumor microenvironment) and serum-grown culture conditions by RT-qPCR." (PMID 34295384, 2021). "Second, we found that the downregulation of FOXK1 decreased FHL2 expression, whereas downregulation of FHL2 decreased FOXK1 expression in three colon cancer cell lines." (PMID 27892920, 2016). "In gastric and colon cancer cell lines, suppression of FHL2 inhibited anchorage-dependent and -independent cell growth, and tumor formation in nude mice xenograft." (PMID 19018287, 2008). "Suppression of FHL2 by antisense and siRNA methods has been shown to inhibit growth of gastric and colon cancer cell lines." (PMID 19018287, 2008). "Whether the suppression of FHL2 by miR-340-5p in colon cancer also have the ability to inhibit other oncogenes remains to be demonstrated." (PMID 34295384, 2021). "The current study hypothesized that targeting FHL2 expression by miR-340-5p in colon cancer may attenuate colon cancer cell migration and invasion." (PMID 34295384, 2021). "Furthermore, levels of miR-340-5p were significantly lower in serum-grown cancer cells compared to low-serum cultured cells, indicating an inverse relationship between FHL2 mRNA and miR-340-5p in colon cancer cells." (PMID 34295384, 2021). "In addition, we also analyzed FHL2 expression among some common colon cancer cell lines and found that FHL2 expression was relatively low in HT-29 and HCC2998 cell lines compared to other cell lines such as CaCo2, DLD-1, HCT116, HCT15, LoVo, SW480 and TC71." (PMID 34295384, 2021). "Analysis of GSE97023 microarray dataset revealed that commonly used colon cancer cell lines have two different levels of FHL2 expression, indicating that colon cancer might have two different levels of FHL2 expression depending on the colon cell lines." (PMID 34295384, 2021). "It was found that miR-340-5p regulates colon cancer cell invasion and migration by targeting FHL2." (PMID 34295384, 2021). "Endogenous p57/FHL2 complexes were detected in the cervix carcinoma cell line HeLa and the colon carcinoma cell line HRT-18 which may indicate a general functional role of this interaction, not restricted to specific tissues or tumor cell types." (PMID 32346031, 2020). "Thus, finding a way of controlling both FHL2 and E-cad could potentially be a therapeutic approach in antagonizing colon cancer metastasis." (PMID 34295384, 2021). "Thus, targeting of FHL2 by miR-340-5p could be a useful strategy to inhibit colon cancer metastasis." (PMID 34295384, 2021). "The specific TSB also reversed the miR-340-5p mimic-induced FHL2 expression in colon cancer cells, suggesting that the binding site for miR-340-5p on FHL2 mRNA is a functional binding site and it regulates the process of colon cancer cells migration and invasion." (PMID 34295384, 2021). "Moreover, inhibition of FHL2 attenuates cancer cell proliferation and increases E-cad expression in colon cancer cells, suggesting that targeting FHL2 by miR-340-5p might be a useful approach to antagonize colon cancer cell metastasis." (PMID 34295384, 2021). "One previous report identifies Snail1 as a binding protein of FHL2 and suggests that by interacting with Snail1, FHL2 inhibits E‐cadherin transcription activity, which promotes the EMT process in colon cancer cells." (PMID 29193729, 2018).
colon carcinoma (continued). "Datasets GDS4382 and GSE115313 analysis revealed that colon cancer tissue had significantly lower levels of FHL2 expression than matched normal non-cancerous colonic tissue." (PMID 34295384, 2021). "This might be regulated by intramembrane proteolytic cleavage mechanism that causes shedding of EpEx and translocation of the cytoplasmic domain in the cytoplasm, binding to FHL2 and β-catenin and translocation into the nucleus (Ep-ICD) in colon cancer cells." (PMID 25695234, 2015). "However, the interaction between miR-340-5p and FHL2 and their role in regulating colon cancer cell migration and invasion has not yet been investigated." (PMID 34295384, 2021). "However, the role of FHL2 in colon cancer migration and invasion has not been examined." (PMID 34295384, 2021).